MYC (MYC proto-oncogene, bHLH transcription factor)
Diseases named in the same sentence as MYC in open-access papers (continued):
Sharing a sentence is not in itself a finding about the gene and the disease.
breast cancer (continued). "Among these candidates, we focused on the spliceosome inhibitor based on the correlation of spliceosome inhibition and MYC activation as reported in breast cancer, lymphomagenesis, and glioblastoma stem cells which overexpress MYC, but has not as yet been examined in SCLC." (PMID 28192473, 2017). "Just to give a few examples, MYC alterations and amplifications are poor prognostic markers or late events in our three most common types of cancer, lung cancer, prostate cancer, and breast cancer." (PMID 28333115, 2017). "The role of MYC in breast cancer has been highlighted by the participation of its target genes in cell growth, transformation, angiogenesis, and cell-cycle control, and also the fact that breast cancer 1 protein is involved in transcriptional regulation via interaction with MYC." (PMID 28480695, 2017). "Taken together, these data reveal that HN1 promotes the progression of breast cancer by upregulating MYC expression, and might be a therapeutic target for breast cancer." (PMID 28490334, 2017). "Proto-oncogene MYC, also named c-Myc and bHLH transcription factor, is an indispensable signal core in a variety of biological processes that support the growth of various types of cancer, such as ovarian cancer, endometrial cancer, breast cancer and so on." (PMID 29212204, 2017). "However, prognostic and clinicopathological significance of MYC in breast cancer need further evaluation." (PMID 29212204, 2017). "In addition, c-MYC is a radiosensitive locus that is altered by translocations or amplifications following radiation therapy of breast cancer cells, emphasizing its role in radiogenic breast cancer progression and recurrence." (PMID 28333115, 2017). "Although the role of CCAT2 in up-regulation of MYC expression has been demonstrated in colon cancer in vitro, there is no sufficient data regarding the possible interactions of these two genes in the tumorigenesis process in breast cancer samples." (PMID 28480695, 2017). "To determine whether the reduced expression of let-7a/b was responsible for p62-mediated stabilization of MYC mRNA, we co-transfected let-7a/b mimics with p62 in breast cancer cells." (PMID 27345399, 2017). "In human breast cancer, Pvt1 has been proposed to act by stabilizing MYC protein." (PMID 28875933, 2017). "We further demonstrated whether HN1 can regulate the proliferation and invasiveness of breast cancer and the self-renewal of BCSCs by regulating MYC expression." (PMID 28490334, 2017). "In Du145 cells, the overexpression of HAPTOV1 also associated to significantly increased levels of stemness genes LIN28A, ALDH1A1 and MYC, whereas in PC3 cells it associated to a significant expression of LIN28A, MYC, NANOG and POU5F1 genes, in agreement with reports in breast cancer cells." (PMID 28938627, 2017). "A recent study found that the spliceosome, a dynamic macromolecular ribonucleoprotein (RNP) complex that catalyses the splicing of nuclear pre-mRNA into mRNA, is a therapeutic vulnerability in breast cancer models driven by MYC, due to MYC-induced elevation of mRNA synthesis." (PMID 28192473, 2017). "Upregulation of AMPK and mir33a results in down-regulation of MYC in breast cancer models." (PMID 28362357, 2017). "Downregulation of MYC abrogated the effect of HN1 overexpression in breast cancer cell lines." (PMID 28490334, 2017). "MYC is the well-known oncogene in breast cancer and many other cancer types." (PMID 27034728, 2016). "MYC is a target of WNT/β-catenin signaling, which induces epigenetic repression of BRCA1 expression by means of snail family zinc finger 2 (SNAI2) and is associated with basal-like breast cancer and EMT, including metastasis." (PMID 27590516, 2016).
breast cancer (continued). "MYC and FOXM1 have been previously associated with breast cancer growth." (PMID 26894864, 2016). "In breast cancer, the gene expression profile of tumors with FDG SUVmax > 10 showed an “FDG signature” that was enriched with glycolysis-related genes and associated with activation of the MYC transcription factor (c-Myc), a functional counterpart of MYCN." (PMID 26959748, 2016). "We induced MYC in T47D breast cancer cell line with FBS treatment after serum starvation." (PMID 27034728, 2016). "This confirms the strong effect of PAC on ERα in ERα− breast cancer cells and indicates that this gene as well as its targets c-MYC and CCND1 might play important roles in the response of these cells to PAC." (PMID 27465411, 2016). "Copy number aberrations (CNAs) in known breast cancer driver genes present in the PDTXs included gains/amplifications of MYC (78%), CCNE1 (34%), ZNF703 (25%), CCND1 (31%), MDM2 (25%), and ERBB2 (9%) and deletions of PTEN (41%), PPP2R2A (72%), CDKN2A (47%), and CDKN2B (47%)." (PMID 27641504, 2016). "Multivariate cox regression analysis for predictors of breast cancer specific survival within the whole cohort and ER+ positive cases showed that ADA3/c-MYC co-expression is significantly associated with patients’ outcome independently of tumor grade, stage, size and ER status." (PMID 27852327, 2016). "In this study we used the available ADA3 and c-MYC expression data to assess if ADA3 and MYC expression correlates with each other and whether their relative expression patterns predict outcomes in ER+ breast cancer patients." (PMID 27852327, 2016). "In addition, CDK1 was optionally lethal to MYC-dependent human breast cancer cells, suggesting further investigation of CDK1 inhibition as a potential therapy for this type of breast cancer." (PMID 27149165, 2016). "MYC is a well-known oncogene for breast cancer, as well as many other cancer types." (PMID 27034728, 2016). "Furthermore, the frequency and magnitude of c-MYC amplification and protein expression were significantly higher in tissue from radiation-related breast cancers compared to that in cases unrelated to radiation." (PMID 27417356, 2015). "Similarly to surveys of canine mammary carcinomas and canine osteosarcomas, the frequently gained region on CFA13 included the MYC gene in the mammary tumours of the present study." (PMID 25955013, 2015). "Finally, pharmacological inhibition of the core spliceosome component SF3B1 reduced the tumorigenic and metastatic potential of MYC-driven human breast cancer cell lines." (PMID 26490253, 2015). "Similarly, the high activity of MYC signaling in luminal-B breast cancers is consistent with the frequent amplification of its locus in this subtype of breast cancer." (PMID 25886003, 2015). "In trastuzumab-treated breast cancer cells NCOR2/SMRT interacts with MYC." (PMID 26117541, 2015). "Breast cancer cells with low MYC expression, such as Luminal A, may be more sensitive to small fluctuations in MYC protein levels which arise from altered FBXW7 expression." (PMID 25669969, 2015). "Furthermore, 4 of 9 (44%) radiogenic breast cancer cases had at least 10% of nuclei with 6 or more c-MYC signals, compared with only 1 of 20 (5%) sporadic breast cancer cases (Fisher's exact test, P=0.022)." (PMID 25531321, 2015). "c-MYC activation that depends on LINE-1 insertion has been reported in breast cancer." (PMID 25821563, 2015). "Paradoxically, however, a prominent study by Liu and colleagues demonstrated that c-MYC is in fact a metastasis suppressor, with over-expression of c-MYC suppressing both the in vitro invasiveness and in vivo metastatic capacity of human breast cancer cell lines." (PMID 26384308, 2015). "However, comparison of protein expression in c-MYC-positive tumours demonstrated that the expression was significantly higher in the radiogenic breast cancer compared with sporadic breast cancer (Mann–Whitney U-test: P<0.001)." (PMID 25531321, 2015).
breast cancer (continued). "MYC can increase the dependency of breast cancer cells on glutamine and glucose for cell survival." (PMID 25693144, 2015). "Interestingly, the mechanisms through which MYC appears to alter splicing in the context of lymphomagenesis differ from those in breast cancer." (PMID 26490253, 2015). "Some regions statistically associated with grade III tumors in our study harbor genes either frequently amplified in aggressive breast cancer such as the oncogenes MYC (8q24) and CCNE1 (19q12) or already reported as deleted in breast tumors such as MTAP (9p21)." (PMID 25391423, 2015). "Two recent studies of lymphoma and breast cancer have identified components of the spliceosome — the core splicing machinery — that are essential for malignant transformation driven by the transcription factor MYC." (PMID 26490253, 2015). "An amplification of the c-MYC oncogene for example is found in 15.7% of human breast cancers." (PMID 26132936, 2015). "In human breast cancer, amplification of the MYC gene is a quite frequent event." (PMID 25955013, 2015). "The MYC oncogene is a frequently amplified in human cancer and a recent synthetic lethal shRNA screen identified SAE1 and SAE2 (the two heterodimer components of the SUMO E1) as top hits that confer synthetic lethality in breast cancer cells with high MYC activity." (PMID 25860128, 2015). "Additionally, CIP2A signature reveals the c-MYC dependency of CIP2A-regulated phenotypes and its association with breast cancer subtypes." (PMID 25726524, 2015). "The MYC oncogene is co-amplified with TRPS1 in breast carcinomas with increased proliferation rate." (PMID 26183398, 2015). "Amplification of MYC has been reported in breast cancer as well as in many other cancers." (PMID 24591761, 2014). "It has also been identified as a MYC cofactor and correlates with poor breast cancer outcomes." (PMID 24489661, 2014). "Furthermore, the c-MYC gene plays an important role in the promoter region of hTERT, which is widely over expressed in breast cancer." (PMID 24460895, 2014). "It is known that MYC deregulation contributes to breast cancer development and progression." (PMID 24550933, 2014). "Notwithstanding, several converging studies have suggested that MYC may play an important function in breast cancer." (PMID 24591761, 2014). "CIP2A signature revealed the MYC dependency of CIP2A-regulated phenotypes in the breast cancer." (PMID 25015035, 2014). "While rapid drug metabolism limits the efficacy of 10058-F4 as an antitumor agent for solid tumors, its use in vitro showed that inhibiting MYC in antiestrogen resistant breast cancer cells confirmed the essential role of MYC activation in driving this phenotype." (PMID 25339305, 2014). "Clinical covariates were used only for the method Cli, including the following attributes: age at diagnosis, MYCN status and INSS stage for neuroblastoma; age, smoking status, gender, stage, and MYC status for lung adenocarcinoma; age, stage, size of tumor, and grade for breast cancer." (PMID 25295525, 2014). "This R-loop-mediated mechanism of c-MYC gene regulation may be relevant to tumour progression in breast cancer, which frequently shows overexpression of both c-MYC and TDRD3." (PMID 25233079, 2014). "Thus, safely targeting glutamine metabolism is a promising strategy to treat MYC-driven antiestrogen resistant breast cancer." (PMID 25339305, 2014). "Thus, despite that the expression of MYC is significantly different between breast cancer patients and healthy controls, correlation between MYC amplification and different clinicopathological parameters are inconsistent." (PMID 24591761, 2014). "Furthermore, inhibition of aminotransferases prevents xenograft tumor growth of MDA-MB-231 breast cancer cells and MYC-dependent neuroblastoma cells." (PMID 24280108, 2013).
breast cancer (continued). "We found that DACT1, located mainly in the cytoplasm and membrane, reduced the expression of active β-catenin and its downstream target gene c-MYC in breast cancer cells, thus inhibiting cell proliferation of breast cancer by inducing apoptosis, as well as tumor cell migration." (PMID 23497530, 2013). "Notably, four C-oncogenes (NOTH1, FGFR2 and MYC for the breast cancer and FGFR3 for the colorectal cancer) were found to be amplified but down-regulated in their corresponding cancer types." (PMID 23472150, 2013). "Targeting MYC-regulated pathways in combination with inhibitors of other oncogenic pathways may provide a promising therapeutic strategy for breast cancer, the basal-like subtype in particular." (PMID 23874497, 2013). "MYC is overexpressed in the basal-like subtype and may serve as a target for this aggressive subtype of breast cancer." (PMID 23874497, 2013). "Also CCND1 expression, reportedly down-regulated in breast cancer, was confirmed in our profile, through the down-regulation of MYC, reported to be coupled with CCND1 expression." (PMID 23405235, 2013). "Indeed, MYC is one of 157 genes in “amplicon 8q23-q24” previously identified in an extensive study of the breast cancer “amplicome” derived from 191 samples." (PMID 23468608, 2013). "We aimed to evaluate whether the hormone receptor expression, HER2 and MYC genes and their protein status, and KRAS codon 12 mutations may be prognostic or predictive biomarkers of breast cancer." (PMID 23555992, 2013). "Our findings indicate p21/p16 and BMI1/c-MYC could serve as functional targets of dietary factor, GE, to inhibit early breast carcinogenesis and prevent breast cancer." (PMID 23342141, 2013). "MYC expression is primarily driven by the P2 promoter in human breast cancer cell lines." (PMID 23145106, 2012). "It modulates c-MYC and acts as an oncogene in human T-cell leukaemia and mouse mammary cancers." (PMID 22223089, 2012). "To determine whether RAD21 binding to regulatory elements could contribute to differences in MYC expression between breast cancer cell lines, we performed RAD21 ChIP on MCF7, T47D and MDA-MB-231 cells cultured in their respective complete media." (PMID 23145106, 2012). "A study showing that RAD21 depletion prevents estrogen-induced G0/G1-S transition in breast cancer cells is consistent with regulation of MYC by cohesin, since a large proportion of genes involved in estrogen-stimulated cell cycle progression are downstream of MYC." (PMID 23145106, 2012). "To determine whether cohesin regulates MYC in human breast cancer cell lines we transfected MCF7 cells with siRNA targeting the RAD21 subunit of cohesin." (PMID 23145106, 2012). "In addition, our data show that even a partial reduction of RAD21 completely blocks the transcriptional response of MYC to estradiol, or other growth regulatory pathways, in breast cancer cell lines." (PMID 23145106, 2012). "Therefore, in the majority of breast cancers, over-expression of MYC is likely to be due to dysregulation of transcription, translation or protein stability." (PMID 23145106, 2012). "Finally, our results suggest that the observed reduction of NDRG2 mRNA in breast cancer correlated weakly with MYC mRNA expression." (PMID 21226903, 2011). "Further investigations identified the isopeptidase activity of Jab1 to be critical for its ability to promote transformation and progression in breast epithelial cells and inhibition of this activity is sufficient to block breast cancer progression driven by MYC and RAS." (PMID 21689417, 2011). "Furthermore, we used quantitative real-time RT-PCR to quantify the levels of NDRG2 and MYC mRNA in thyroid gland cancer and breast cancer, using a distinct set of normal and tumor samples." (PMID 21226903, 2011). "In the same set of breast cancer samples, we quantified the level of MYC mRNA." (PMID 21226903, 2011).
breast cancer (continued). "Importantly, patient survival was significantly reduced in breast cancers where MYC and ErbB2 are co-amplified." (PMID 20840765, 2010). "Thus, in addition to the (IL12, TGFB) interaction, we observed that high EGFR and low IL12 activity provided a better prognostic model in ER- breast cancer, while simultaneous high MYC high RAS activity defined a better prognostic model in ER+ breast cancer." (PMID 21050467, 2010). "Furthermore, this study led us to select c-MYC as a candidate to be tested in in vitro and in vivo models, regarding future treatments for breast cancer which is de novo resistant to trastuzumab." (PMID 19118495, 2009). "Instead, c-MYC was identified as a novel potential target protein in breast cancer cells." (PMID 19118495, 2009). "Thus the strong transcriptional effect of MYC that we have detected suggests that more than altered MYC expression is contributing to its activity in basal breast cancer." (PMID 19270750, 2009). "EBV oncogene LMP1 in NPC, PTGS2 in endometrial carcinoma and MYC in breast cancer may induce the BIRC5 expression by different pathways." (PMID 18570662, 2008). "In some sporadic breast cancers, the poor outcome associated with BRCA1 methylation and low levels of expression could be explained by MYC amplification." (PMID 17987116, 2007). "We included MYC in the protocol because BMI1 was originally identified as an oncogene that cooperates with MYC in lymphoma production in mice, MYC is commonly amplified in human breast cancer, and several groups have reported that MYC is required for HMEC transformation." (PMID 17573968, 2007). "In 80% of breast cancers, c-MYC is over-expressed, indicating that its potential miRNA regulator could be down-regulated in these cases." (PMID 17877811, 2007). "ERα and MYC are frequently over-expressed during breast cancer progression." (PMID 16417658, 2006). "Several of these regions contain genes known to be amplified in breast cancer, including ERBB2, EGFR and MYC, while others include genes not previously implicated in breast cancer, including PTK2." (PMID 16457699, 2005). "Thus, miR-32-5p likely regulates c-MYC through FBXW7 degradation—a pathway conserved in breast cancer but never linked to c-MYC until now." (PMID 40711670, 2025). "Furthermore, circACTN4 overexpression might upregulate the expression of CCNE1 and CDK4 through increasing AcH4 levels of MYC target genes, thereby promoting cell cycle progression and tumorigenesis in breast cancer." (PMID 40612865, 2025). "Rationale for miR-32-5p Investigation in Breast Cancer Despite extensive research on miR-32-5p across various malignancies, its specific regulatory mechanisms in breast cancer remain incompletely characterized, particularly regarding its interaction with key oncogenic drivers like c-MYC." (PMID 40711670, 2025). "For example, BCL2 and MYC, well-known oncogenes that inhibit apoptosis and promote cell proliferation, have been reported to undergo m6A-mediated translation, stabilization, or indirect promotion in bladder cancer, lung cancer, breast cancer, acute myeloid leukemia (AML), and gastric cancer." (PMID 40136363, 2025). "In order to validate the correlation between MYC transcriptional signature and clinical response to PARPis, we analyzed 12 paraffin-embedded pre-PARPi treatment biopsies of patients with metastatic HR-altered breast cancer who were subsequently included in a clinical trial with PARPis." (PMID 41273720, 2025). "Notably, breast cancer tissues with MYC amplification showed palbociclib resistance." (PMID 38424044, 2024). "In addition, IRE1–XBP1 axis, the downstream of the UPR pathway could significantly accentuate MYC-driven tumorigenic progression in breast cancer and urothelial carcinomas." (PMID 39080273, 2024).